CDR2L (cerebellar degeneration related protein 2 like)
Synonyms: HUMPPA
Tractability: PROTAC: ubiquitination databases record sites on it; its protein half-life has been measured.
Gene: Protein-coding gene on chromosome 17 (74,987,583 to 75,005,800, forward strand). Ensembl gene ENSG00000109089.
Subcellular location (Human Protein Atlas): Cytosol
Gene Ontology:
Molecular function: identical protein binding; protein binding
Biological process: Golgi to secretory granule transport; vesicle transport along microtubule
Genetic constraint (gnomAD): Loss-of-function variants: 29 observed, 24.65 expected, observed/expected ratio (o/e) 1.18, 90% interval 0.88 to 1.6. The synonymous counts are far from expectation, so gnomAD's model fits this gene poorly and the ratio says little. Missense variants: 564 observed, 485.45 expected, observed/expected ratio (o/e) 1.16, 90% interval 1.08 to 1.25. Synonymous variants: 281 observed, 220.46 expected, observed/expected ratio (o/e) 1.27, 90% interval 1.15 to 1.41.
Homologues: Orthologues: chimpanzee CDR2L (99% identical), macaque CDR2L (98% identical), dog CDR2L (96% identical), pig CDR2L (95% identical), rat Cdr2l (94% identical), mouse Cdr2l (93% identical), guinea pig CDR2L (92% identical), rabbit CDR2L (89% identical), tropical clawed frog cdr2l (66% identical), zebrafish cdr2l (59% identical), Drosophila melanogaster Cen (27% identical). Paralogues in human: CDR2 (42% identical).
Diseases named in the same sentence as CDR2L in open-access papers:
CDR2L is named in the same sentence as 16 diseases in open-access papers, as found by Europe PMC text mining. Sharing a sentence is not in itself a finding about the gene and the disease. The quoted sentences say what the papers report.
ovarian carcinoma (5 papers, 2023 to 2025). A malignant neoplasm originating from the surface ovarian epithelium. "The observation that loss of either CDR2L or RPS6 causes similar effects on the cell cycle in ovarian cancer cells further supports an association between the two proteins." (PMID 38802745, 2024). "Taken together, these data suggest that loss of CDR2L suppresses cell cycle progression in ovarian cancer, which may trigger apoptosis." (PMID 38802745, 2024). "CDR2L is widely present in ovarian cancer tissues and abundantly expressed in testicular and prostate cancer tissues." (PMID 40595026, 2025). "In conclusion, we found that knockout of CDR2L in an ovarian cancer line dysregulates genes involved in ribosome biogenesis, protein synthesis and cell cycle-related processes, ultimately impairing cell proliferation." (PMID 38802745, 2024). "In the present study, we used a multi-omics approach to explore changes in the transcriptome, proteome, and secretome induced by knockout of CDR1, CDR2, and CDR2L in ovarian cancer cells." (PMID 38802745, 2024). "Previously, we demonstrated that CDR2L colocalizes with ribosomes in ovarian cancer cells and Purkinje neurons." (PMID 38802745, 2024). "CDR2L is widely present in ovarian cancer tissues and is abundantly expressed in testicular and prostate cancer tissues." (PMID 36925652, 2023). "CDR2L has also been suggested as a regulatory gene in ovarian cancer." (PMID 38233508, 2024). "Patients with ovarian cancer (OC) may develop anti‐Yo‐associated paraneoplastic cerebellar degeneration (PCD)—a cerebellar ataxia associated with tumor‐induced autoimmunity against CDR2 and CDR2L proteins." (PMID 39473143, 2024).
Autoimmunity (2 papers, 2018 to 2023). The occurrence of an immune reaction against the organism's own cells or tissues. "However, a recent study has identified that all patients with anti-Yo PCD OT harbour mutations and/or gains in CDR2 and/or CDR2L genes, which could lead to immune tolerance breakdown and autoimmunity." (PMID 29899393, 2018). "In addition, CDR2L has been proposed as the main antigen in PCA-1/Yo autoimmunity, which prompted us to study these antigens across a number of patient groups encompassing known PCA-1/Yo autoimmunity and potential sources of false positives." (PMID 37841252, 2023).
ovarian tumours (2 papers, 2018 to 2024). "Increased expression of CDR2L mRNA has been observed in ovarian tumours from PCD patients with anti-Yo antibodies compared to ovarian tumours from patients without PCD or anti-Yo antibodies." (PMID 38802745, 2024).
bladder cancer (1 paper, 2025). "The PD-1/PD-L1 immunotherapy based on bladder cancer further demonstrated that high levels of FABP4, CDR2L, and FSTL3 expression were associated with a poor response to immunotherapy, confirming the applicability of the associated immune dysregulation across various tissues and diseases." (PMID 40595026, 2025).
breast carcinoma (1 paper, 2023). "CDR2L protein appeared to be the main target of Yo‐antibodies in PCD‐tumors and has been implicated in ovarian and breast cancers." (PMID 37395176, 2023).
colon cancer (1 paper, 2025). "The results indicated that in cases with high expression of FABP4, CDR2L, and FSTL3, immune-related pathways associated with diabetes and colon cancer were significantly enriched." (PMID 40595026, 2025). "To explore the roles of FABP4, CDR2L, and FSTL3 in cellular composition and molecular profiles, we analyzed single-cell RNA-sequencing (scRNA-seq) data from 49,589 cells derived from 23 colon cancer samples (GSE200997)." (PMID 40595026, 2025). "In conclusion, FABP4, CDR2L, and FSTL3 can be used as prognostic markers for colon cancer." (PMID 40595026, 2025).
diabetes (1 paper, 2025). "By integrating multi-omics data from public repositories and applying machine learning-driven feature selection, we identified three core biomarkers—FABP4,CDR2L,and FSTL3 that independently predicted overall survival in CRC patients with diabetes." (PMID 40595026, 2025). "Our findings establish FABP4, CDR2L, and FSTL3 as pivotal regulators at the CRC-diabetes interface, with dual utility as prognostic indicators and predictors of immunotherapy efficacy." (PMID 40595026, 2025).
Myelopathy (1 paper, 2021). Myelopathy is an descriptive term, referring to pathology leading to a neurologic deficit related to the spinal cord. "This case demonstrates the diagnostic utility of unbiased assays in patients with suspected PNDs, supports prior observations that anti-Yo PND can be associated with isolated myelopathy, and implicates CDR2L as a potential antigen in the spinal cord." (PMID 34744969, 2021).
cancer (7 papers, 2020 to 2024). A tumor composed of atypical neoplastic, often pleomorphic cells that invade other tissues. "Previous studies showed that CDR2L localizes to the cell cytoplasm in association with membrane-bound and free ribosomes in both Purkinje neurons and cancer cells." (PMID 38802745, 2024). "Tumour expression and genetic alterations of the CDR proteins, particularly CDR2L, is thought to trigger an immune response which targets both the cancer cells and the Purkinje neurons endogenously expressing the CDR proteins." (PMID 38802745, 2024). "Anti‐Yo targets the cerebellar degeneration‐related proteins CDR2 and CDR2L expressed in both cancer cells and Purkinje cells." (PMID 39473143, 2024). "Consistent with results obtained from the TCGA-COAD cohort, six CRGs, including DPP7, GPRASP1, UNC5C, RAB3B, PCDH9, SLC18A2, were significantly downregulated, whereas CDR2L was upregulated in cancer tissues in comparison with paracancerous normal tissues." (PMID 37384293, 2023). "CDR2 and CDR2L strongly stained the cytoplasm of cancer cells; however, only CDR2L strongly stained the cytoplasm of Purkinje cells." (PMID 36483902, 2022). "When examining the top 100 gene pairs, BSDC1, C3orf14, CDR2L, LRRC42, MEOX2, NRG2, and PLEKHA6, and SCARF1 were consistently identified by feature selection methods to be associated with cancer status." (PMID 33087122, 2020). "C3orf14, CDR2L, LRRC42, MEOX2, NRG2, and SCARF1 have been previously associated with cancer." (PMID 33087122, 2020). "In addition, several positively selected genes, for example, CDR2L, might also involve cancer resistance in elephants." (PMID 37395176, 2023). "In the subsequent cell activity and apoptosis experiments, we found that the low expression of SNAI1, CDR2L, FRMD5, and FSTL3 could reduce the activity of cancer cells and increase the apoptosis rate of cancer cells." (PMID 36925652, 2023). "Interestingly, C3orf14, CDR2L, LRRC42, MEOX2, NRG2, and SCARF1 are known carcinogenic genes, while BSDC1 and PLEKHA6 have not been described in previous cancer literature." (PMID 33087122, 2020).
tumor (5 papers, 2021 to 2024). "The HRI signature consists of 11 HRDEGs, and we focused on the 5 key genes (RGS16, SNAI1, CDR2L, FRMD5, and FSTL3), which exhibited elevated expression levels in tumor tissues and are prognostic risk factors for CC." (PMID 36925652, 2023). "Furthermore, CDR2L protein expression was restricted to HER2 expressing tumor cells in the patient's breast tissue." (PMID 34744969, 2021). "The mRNA expression levels of RGS16, SNAI1, CDR2L, FRMD5, and FSTL3 were higher in tumor samples than that in adjacent normal tissues in TCGA-COAD cohort, suggesting that these five key genes participate in the progression of CC." (PMID 36925652, 2023). "DPP7, CDR2L exhibited higher and UNC5C, RAB3B, SLC18A2, GPRASP1, PCDH9 exhibited lower expression in tumor tissues (P<0.05)." (PMID 37384293, 2023). "The results demonstrated that RGS16, SNAI1, CDR2L, FRMD5, and FSTL3 consistently exhibited significantly higher relative mRNA expression levels in CC tumor samples than in paired adjacent normal tissues." (PMID 36925652, 2023). "Low expression of SNAI1, CDR2L, FRMD5, and FSTL3 could induce cell viability and promote tumor cell apoptosis." (PMID 36925652, 2023).
CDR2L also shares sentences with these, for which no sentence is quoted: prostate carcinoma (2 papers); cerebellar ataxia (1); cerebellar degeneration (1); Lambert-Eaton myasthenic syndrome (1); myasthenia gravis (1); paraneoplastic cerebellar degeneration (1).